KCNJ9 (potassium inwardly rectifying channel subfamily J member 9)
Description:
Inward rectifier potassium channels are characterized by a greater tendency to allow potassium to flow into the cell rather than out of it. Their voltage dependence is regulated by the concentration of extracellular potassium; as external potassium is raised, the voltage range of the channel opening shifts to more positive voltages. The inward rectification is mainly due to the blockage of outward current by internal magnesium, This receptor is controlled by G proteins. Unable to produce channel activity when expressed alone. Forms a functional channel in association with KCNJ3/GIRK1 (By similarity).
Synonyms: GIRK3; Kir3.3
Tractability: Small molecule: it belongs to a druggable protein family. Antibody: its Gene Ontology location is reachable by antibodies, with high confidence; UniProt predicts a signal peptide or a membrane-spanning region. PROTAC: ubiquitination databases record sites on it.
Gene: Protein-coding gene on chromosome 1 (160,081,501 to 160,090,563, forward strand). Ensembl gene ENSG00000162728.
Subcellular location: Membrane
Pathways (Reactome):
Neuronal System: Activation of G protein gated Potassium channels; Inhibition of voltage gated Ca2+ channels via Gbeta/gamma subunits
Gene Ontology:
Molecular function: protein binding; inward rectifier potassium channel activity; G-protein activated inward rectifier potassium channel activity
Biological process: potassium ion import across plasma membrane; potassium ion transport; regulation of presynaptic membrane potential
Cellular component: plasma membrane; inward rectifier potassium channel complex; membrane; parallel fiber to Purkinje cell synapse; presynaptic membrane; voltage-gated potassium channel complex
Genetic constraint (gnomAD): Loss-of-function variants: 19 observed, 25.27 expected, observed/expected ratio (o/e) 0.75, 90% interval 0.52 to 1.1. The upper end of that interval is the gene's LOEUF score, 1.1, which puts it in group 4 of 6, group 1 being the genes least tolerant of losing a copy. Missense variants: 317 observed, 514.79 expected, observed/expected ratio (o/e) 0.62, 90% interval 0.56 to 0.68. Synonymous variants: 222 observed, 228.9 expected, observed/expected ratio (o/e) 0.97, 90% interval 0.87 to 1.08.
Homologues: Orthologues: chimpanzee KCNJ9 (100% identical), guinea pig KCNJ9 (99% identical), pig KCNJ9 (99% identical), rat Kcnj9 (99% identical), mouse Kcnj9 (99% identical), dog KCNJ9 (93% identical), macaque KCNJ9 (93% identical), tropical clawed frog kcnj9 (80% identical), zebrafish kcnj9 (70% identical), rabbit KCNJ9 (61% identical). Paralogues in human: KCNJ6 (69% identical), KCNJ5 (65% identical), KCNJ3 (55% identical), KCNJ12 (50% identical), KCNJ18 (50% identical), KCNJ2 (48% identical), KCNJ14 (48% identical), KCNJ4 (47% identical), KCNJ11 (42% identical), KCNJ8 (41% identical), KCNJ1 (38% identical), KCNJ16 (36% identical), and 3 more.
Diseases named in the same sentence as KCNJ9 in open-access papers:
KCNJ9 is named in the same sentence as 24 diseases in open-access papers, as found by Europe PMC text mining. Sharing a sentence is not in itself a finding about the gene and the disease. The quoted sentences say what the papers report.
epilepsy (5 papers, 2008 to 2025). A brain disorder characterized by episodes of abnormally increased neuronal discharge resulting in transient episodes of sensory or motor neurological dysfunction, or psychic dysfunction. "KCNJ10 and KCNJ9 have also been correlated with the risk of epilepsy." (PMID 40142207, 2025). "Furthermore, the time to remission was correlated with KCNJ10, and KCNV2 and KCNJ9 influenced the classification of epilepsy." (PMID 40142207, 2025). "Finally, epilepsy classification was correlated with KCNV2/rs10967728 and KCNAB1/rs1551066, KCNJ9/rs2753268 (p-values = 0.033, 0.020, 0.024)." (PMID 40142207, 2025).
breast carcinoma (2 papers, 2004 to 2025). "Breast cancer studies included E1 (KCNMB1), E4 (KCNN3), E9 (KCNH1, KCNK15), E15 (KCNT2), E22 (KCNK5, KCNK15), E33 (KCNQ1-OT1), E38 (KCNMA1), E48 (KCNJ9), and E63 (KCNK12)." (PMID 40867621, 2025).
alcohol dependence (1 paper, 2013). Physical and psychological dependence on alcohol. "In particular, Kcnj9 has been identified as a potential quantitative trait gene (QTG) for sedative-hypnotic withdrawal from ethanol, residing on mouse chromosome 1 syntenic to region of human chromosome 1 that has been identified for alcohol dependence." (PMID 24312422, 2013).
Anxiety (1 paper, 2018). Intense feelings of nervousness, tension, or panic often arise in response to interpersonal stresses. "Thus, our results support a broad role for Alcw11/Kcnj9 in ethanol withdrawal (convulsions and anxiety-like behavior) as well as reward phenotypes." (PMID 30210527, 2018).
breast tumors (1 paper, 2019). "Interestingly, among the top dysregulated hits, a set of genes (DEDD, ABCB10, UAP1, KCNJ9, and PSAT1) are located close together on chromosome 1q23.3–42.1 and are co-amplified in >15% of breast tumors from 164 cancer genome studies." (PMID 31253784, 2019).
cocaine dependence (1 paper, 2023). A psychologically and socially impaired state, with or without physiological changes, that develops as a result of using cocaine and which leads to compulsive behaviors to acquire the substance. "Genetic variants in potassium channel signaling, such as KCNJ9, were previously linked to cocaine dependence." (PMID 37730558, 2023).
Cognitive impairment (1 paper, 2019). Abnormal cognition is characterized by deficits in thinking, reasoning, or remembering. "Among the significantly enriched signaling pathways from KEGG analysis, oxytocin signaling pathway (PATH:04921; Cacng2, Adcy1, Kcnj4, Kcnj9, Adcy8, Pik3cd, Elk1, Adcy4, Camkk2, Cacng7, Nos3, Kcnj2) may play an important role in the sevoflurane-induced cognitive impairment." (PMID 31582589, 2019).
migraine (1 paper, 2007). "Overall our studies investigating potential migraine candidate genes in the chromosome 1q23 and 1q31 regions did not provide evidence implicating any of the tested variants of the ATP1A4, CASQ, KCNJ9 and 10, FasL, CACNA1AE genes in migraine." (PMID 17727731, 2007). "Six markers localised to the C1q23-C1q31 region covering several genes of interest (ATP1A4, CASQ1, KCNJ9 and J10, FasL and CACNA1E), have been analysed in regard to their potential association with migraine in a large population (243 migraineurs versus 243 healthy individuals)." (PMID 17727731, 2007).
multiple sclerosis (1 paper, 2007). A progressive autoimmune disorder affecting the central nervous system resulting in demyelination. "We tested polymorphisms from the KCNJ9, KCNJ10 and FasL genes (markers that had previously been tested in a number of other genetic disorders, including Multiple Sclerosis (MS))." (PMID 17727731, 2007).
peripheral nerve injury (1 paper, 2024). Injury to a peripheral nerve. "Kcnj9 encodes the GIRK3 (Kir3.3) subunit of the G protein-gated inwardly rectifying potassium channel in the DRG and is involved in rat with peripheral nerve injury." (PMID 39542827, 2024).
tumor (2 papers, 2005 to 2024). "Among these 10 genes HDAC1, CASP3, REST, HMG20B, FZD7,GNAI3, FZD1 and EPHB4 had elevated expression in tumor group compared to the normal group, while KCNJ9 and SCRT1 were decreased." (PMID 38629068, 2024).
neurodevelopmental disorder (1 paper, 2022). A behavioral and cognitive disorder with onset during the developmental period that involves impaired or aberrant development of intellectual, motor, or social functions. "Interestingly, peripheral LPS exposure led to downregulation of some genes such as Kcnj9 and Kif21b, the deficiency of which has been associated with the occurrence of neurological and neurodevelopmental disorders, again highlighting the importance of the immune system-brain axis." (PMID 36040311, 2022).
neurological disorders (1 paper, 2023). "This clinical case demonstrates a possible association of a single nucleotide substitution in the KCNJ9 gene with neurological disorders (neonatal seizures or a syndrome that has neonatal seizures among its early manifestations)." (PMID 36833293, 2023).
KCNJ9 also shares sentences with these, for which no sentence is quoted: Seizure (2 papers); cancer (1); Down syndrome (1); generalized epilepsy (1); genetic disorders (1); glioma (1); hyperkinetic disorder (1); Keppen-Lubinsky syndrome (1); lung carcinoma (1); temporal lobe epilepsy (1); type 2 diabetes (1).